RAD52 (RAD52 DNA repair protein)
Diseases named in the same sentence as RAD52 in open-access papers (continued):
Sharing a sentence is not in itself a finding about the gene and the disease.
tumor (continued). "In a stark contrast, depletion of Rad52 in FANCM KO cells completely suppresses tumor growth." (PMID 30022024, 2018). "We demonstrated that loss of Rad52 not only increases the death of cells undergoing carcinogen-induced transformation in vivo, but that Rad52 loss also augments in vivo antitumor activity through an enhanced capacity for direct killing of LLC tumor cells by stimulated Rad52−/− NK and CD8+ T cells." (PMID 28415565, 2017). "In this case, homologous repair by Rad52 may be allowing tumor cells to retain adequate stability in the face of DNA-damaging agents in order to thrive and progress towards malignancy." (PMID 28415565, 2017). "Therefore, inactivation of Rad52 could be reasonable approach for the treatment of a BRCA-defective subset of tumours." (PMID 36010882, 2022). "Thus, targeting RAD52 may enhance treatment of BRCA-deficient tumors, but co-inhibition of RAD52 and EEPD1 would likely be self-defeating, enhancing tumor cell survival and potentially enhancing tumor progression by allowing severely damaged cells to survive." (PMID 35155245, 2022). "Thus, simultaneous inhibition of RAD52 and PARP1 might result in a robust dual synthetic lethality, effectively eradicating BRCA1/2-deficient tumor cells." (PMID 31615159, 2019). "Suppression of Rad52 expression in combination with FANCM knockout drastically reduces cell and tumor growth, suggesting a synthetic lethality interaction between these two genes, which offers a potential targeted treatment strategy for FANCM-deficient tumors with Rad52 inhibition." (PMID 30022024, 2018). "The specific HRR mutations identified in the 21 tumour samples were: BRIP1 (n = 5), CDK12 (n = 3), RAD54L (n = 2), RAD51B (n = 2), RAD54L rearr (n = 1), ATM rearr (n = 1), FANCA rearr (n = 1), FANCD2 (n = 1), FANCL rearr (n = 1), FANCL (n = 1), RAD51C (n = 1), RAD52 del (n = 1), XRCC3 rearr (n = 1)." (PMID 30353044, 2018). "Thus, it was hypothesized that decreased expression of Rad52 may enhance DNA DSBs by impairing repair and allowing overwhelming DNA damage to accumulate, resulting in decreased viability and a slower rate of tumor cell outgrowth." (PMID 28722656, 2017). "However, the results of this study suggest that Rad52 activity could occur as part of the tumor cell defense, aiding in malignant progression to enhance tumor cell viability." (PMID 28415565, 2017). "It is possible that loss of Rad52 within the immune cells is not the direct issue and the heightened immune response is actually due to an environmental shift within the host or the tumor microenvironment that alerts the immune system and enhances the immune response." (PMID 28415565, 2017). "Therefore, a therapeutic strategy that targets tumor-specific DNA repair pathways through RAD52 inactivation may be a promising approach to improve therapy efficacy since it can result in an increased tumor cells sensitization to cell death and a decreased toxicity to normal cells." (PMID 31652722, 2019). "Interestingly, NEIL1, RAD52, and POLD4 showed overexpression in the adjacent mucosa compared to tumor tissue." (PMID 41275076, 2025). "Finally, the RAD52 inhibitor D-I03 synergized with a PARP inhibitor to reduce cell viability and tumor burden and prolong survival." (PMID 41040355, 2025). "Inhibition of the KAT2A-SRSF11 axis can promote RAD52 exon 10 skipping, thereby suppressing the interaction of RAD52 with RAD51, impairing HR and promoting radiation-induced tumor cell death across preclinical models, positioning this pathway as a therapeutic vulnerability." (PMID 41198615, 2025). "Therefore, when BRCA-pathway is depleted, RAD52 activity can act as an alternative mediator, replacing the role of BRCA1-PALB2-BRCA2 pathway and promoting tumor cells growth." (PMID 31652722, 2019).
tumor (continued). "It has also been shown that RAD52 is needed for cyclin E-overexpressing cells to progress through G1 to S phase and RAD52 knockout reduces tumor progression in APC (adenomatous polyposis coli gene) mutant mouse tumor models." (PMID 31569559, 2019). "Our results demonstrate that Rad52 depletion increased cell death, decreased myeloid cell frequency, and augmented the incidence and activity of CD8+ T cells and NK effectors that ultimately led to reduced tumor growth." (PMID 28415565, 2017). "More intriguingly, RAD52 depletion is also synthetically lethal with defects in BRCA1, a tumor suppressor that acts upstream of BRCA2 in HR and at the branch point in the DSB repair that promotes homology-directed DNA repair through HR or SSA over the NHEJ (non-homologous end joining)." (PMID 27434671, 2016). "While statistically significant, the eQTL for rs10849605 accounted for only a small proportion of the variance (approximately 4%) in RAD52 expression in HNSC and LUSC tumours, an observation in line with the relatively modest genetic risk observed with this variant." (PMID 25793373, 2015). "Therefore, specific RAD52 inhibitors are expected to selectively kill cancerous cells lacking one of these three tumor suppressors." (PMID 27434671, 2016). "Thus, lack of functional RAD52 may reduce the mutagenic effects of SSA and contribute to tumor suppression." (PMID 32255263, 2020).
neurodegenerative disease (2 papers, 2019 to 2025). A disorder of the central nervous system characterized by gradual and progressive loss of neural tissue and neurologic function. "This highlights the significance of RAD52 in maintaining neuronal integrity and its potential role in the progression of neurodegenerative diseases." (PMID 39796194, 2025). "Interestingly, analysis of sequencing data from the GEO database related to neurodegenerative diseases reveals a potential link between RAD52 and neurodegenerative diseases." (PMID 39796194, 2025). "We hypothesize that RAD52 deletion might lead to mitochondrial dysfunction, subsequently contributing to the development of neurodegenerative diseases." (PMID 39796194, 2025). "Subsequently, to explore whether RAD52 affects shared genes in these neurodegenerative diseases, Venn analysis was conducted on the DEGs from five neurodegenerative diseases to identify shared differential genes." (PMID 39796194, 2025). "However, the potential connection between RAD52 and neurodegenerative diseases remains unknown." (PMID 39796194, 2025).
infection (1 paper, 2012). The state of being infected such as from the introduction of a foreign agent such as serum, vaccine, antigenic substance or organism.
RAD52 also shares sentences with these, for which no sentence is quoted: colorectal cancer (2 papers); Abdominal obesity (1); acute lymphoid leukemia (1); blood cancers (1); cannabis dependence (1); familial breast cancer (1); glioma (1); head and neck squamous cell carcinoma (1); Hereditary breast cancer (1); Hypertension (1); liver cancer (1); Myelodysplasia (1); myelogenous leukemia (1); myeloma (1); myeloproliferative disorder (1); neuroblastoma (1); non-small cell lung carcinoma (1); renal carcinoma (1); salivary gland tumor (1); ulcerative colitis (1).